CASP9 (caspase 9)
Diseases named in the same sentence as CASP9 in open-access papers (continued):
Sharing a sentence is not in itself a finding about the gene and the disease.
Thrombocytopenia (1 paper, 2019). A reduction in the number of circulating thrombocytes. "While the use of ABT-263 in patients is dose-limited due to causing thrombocytopenia via suppression of BCL-xL in platelets, loss of caspase-9 confers resistance to ABT-737, suppressing phosphatidylserine exposure and delaying APT-737-stimulated thrombocytopenia in vivo." (PMID 30791448, 2019).
tongue squamous cell carcinoma (1 paper, 2017). A squamous cell carcinoma that arises from the tongue. "EEP inhibited cell viability and induced apoptosis by upregulation of caspase-3, caspase-8, and caspase-9 in human tongue squamous cell carcinoma cell line." (PMID 28167973, 2017).
Uterine leiomyoma (1 paper, 2019). The presence of a leiomyoma of the uterus.
uveitis (1 paper, 2023). An inflammatory process affecting a part of or the entire uvea. "A study investigated the role of apoptosis in experimental autoimmune anterior uveitis solution and reported that Caspase 9 and Caspase 3 levels increase due to uveitis." (PMID 37051104, 2023). "Looking at the Caspase 9 and Caspase 3 mRNA expression in the eye tissues of the uveitis group, a statistically remarkable difference raised compared with the healthy group (P<0.001)." (PMID 37051104, 2023). "In the present study, Caspase 9 and Caspase 3 levels increased in the uveitis group." (PMID 37051104, 2023). "AGO and RAME decreased Caspase 9 and Caspase 3 levels stimulated by uveitis." (PMID 37051104, 2023).
VRSA infection (1 paper, 2023). "In accordance, VRSA infection provoked upregulated relative mRNA expression levels of pro-inflammatory genes (IL-1β, TNF-α, and IL-6) and apoptosis-associated genes (caspase-3, caspase-9, and Bax)." (PMID 38282617, 2023).
cancer (539 papers, 2002 to 2026). A tumor composed of atypical neoplastic, often pleomorphic cells that invade other tissues. "Caspase-9 activation is a hallmark of mitochondria-dependent apoptosis, a pathway commonly exploited by chemotherapy drugs to induce cancer cell death." (PMID 40649817, 2025). "Genetic polymorphisms in the CASP9 gene have been linked to altered cancer risk across multiple tumor types, suggesting their potential role in modulating apoptosis and tumorigenesis." (PMID 40538398, 2025). "The main Caspases implicated in cancer cell death through apoptosis include Caspase-8, Caspase-9, and the executioner Caspases, specifically Caspase-3 and Caspase-7." (PMID 40490812, 2025). "Increased expression of Ube2l6 is linked to degradation/suppression of cancer cells and affected downstream apoptotic factors (i.e. Caspase 3, Caspase 9, Bcl-2, Bax)." (PMID 38650655, 2024). "The expression levels of caspase-9 and associated proteins in the intrinsic apoptosis pathway are response markers used to predict therapeutic effect in cancer." (PMID 37186587, 2023). "Saman Sargazi's experiments demonstrated that CASP9 rs4645981 and rs1052571 polymorphisms are associated with overall cancer risk." (PMID 36911522, 2023). "They led to a comparable reduction in MCTS as well as microtumour mass by inducing apoptosis in cancer cells, associated with overexpression of caspase 9 and enhanced ROS levels." (PMID 35796910, 2022). "Genistein also induced apoptosis in human cancer cells by triggering both caspase-3 and caspase-9 activity, causing cell death by inhibiting NF-κB signaling and altering levels of the antiapoptotic protein Bcl-2 and proapoptotic protein." (PMID 35630647, 2022). "The locus contains numerous cancer-associated genes (CASP9, SDHB, and others), including chromodomain helicase DNA binding domain 5 (the CHD5 gene), which was recently identified as a tumor suppressor in vivo." (PMID 34205964, 2021). "It is known that miR-133 regulates cancer cell apoptosis with suppression of caspase-9 whereas miR-24 enables cancer cells to survive by targeting X-linked inhibitor of apoptosis (XIAP) which suppresses apoptosis by downregulation of caspases." (PMID 33750303, 2021). "The molecular mechanism of fascaplysin-induced apoptosis is directly linked to activation of the caspase-3, caspase-8, and caspase-9 pathways, cleavage of Bid, release of cytochrome C into cytosol and downregulation of the Bcl-2 level in cancer cells." (PMID 34440090, 2021). "Several intron and promoter region polymorphisms in CASP9 have been associated with incidence and progression of various cancers, including lung, esophagus, liver, breast, and hemopoietic malignancies." (PMID 34305609, 2021). "SNPs located either in the promoter region (CASP9-1263A>G, CASP9 -712C>T, CASP9 -293 del) or in the exonic region (CASP9 Ex5 +32G>A) of Caspase 9 are known to modulate the susceptibility to cancer." (PMID 34530993, 2019). "Although several studies have reported the association of CASP9 Ex5 +32G>A polymorphism with cancer susceptibility, the results of present study however, failed to reveal significant association of this polymorphism with the development and progression CML." (PMID 34530993, 2019). "Many previous studies have shown that polymorphisms in CASP9 were associated with various cancer types, especially in the promoter region." (PMID 28453560, 2017). "We believe when internalized, cetuximab-IONPs accumulate and a pro-apoptotic signal is triggered, as the consequence of EGFR signaling dysregulation, through cleavage of caspase 9, followed by cleavage of caspase 3 that eventually causes cancer cell death." (PMID 25871395, 2015). "The Apaf-1 protein binds and cleaves caspase-9 preproprotein, releasing the mature, activated caspase-9, which stimulates a subsequent caspase cascade that causes the cancer cell to undergo apoptosis." (PMID 25624917, 2015).
cancer (continued). "In this meta-analysis, including a total of 1668 cancer cases and 2294 healthy controls from seven independent studies, we examined the association of the Ex5+32 G>A polymorphism of the CASP-9 gene with cancer risk." (PMID 23251262, 2013). "Polymorphic variation in the CASP-9 gene has been reported to influence cancer risk, especially in the Ex5+32 variant." (PMID 23251262, 2013). "All studies considered, A allele and A allele carriers of Ex5+32 G>A in the CASP-9 gene had significant associations with cancer risk (OR=0.72, 95% CI, 0.58–0.89, P= 0.003; OR= 0.76, 95% CI, 0.63–0.92, P= 0.004; respectively)." (PMID 23251262, 2013). "In conclusion, this meta-analysis of seven case-control studies demonstrated that the CASP-9 Ex5+32 G>A polymorphism is involved in the pathogenesis of variant cancer." (PMID 23251262, 2013). "We demonstrated that A allele and A allele carrier in the Ex5+32 G>A polymorphism had negative associations with cancer susceptibility, which showed a protective effect of the CASP-9 gene against cancer development." (PMID 23251262, 2013). "Twenty-eight studies probing the relationship between CASP9 polymorphisms and cancer susceptibility were identified." (PMID 22616010, 2012). "FAE induced dose and time dependent inhibition of cancer cell growth which was associated with Bax translocation and mitochondria mediated apoptosis with the activation of Caspase 9 dependent Caspase cascade." (PMID 22792212, 2012). "NOS2 was associated with additional cancer biomarkers in these tumors, including pAkt, down stream targets p-caspase-9, and pBAD, as well as the stem cell marker CD44 in ER negative tumors." (PMID 22957045, 2012). "The activity of caspase-3 and caspase-9 is increased in a dose-and time-dependent manner compared with untreated cells in three cancer cells; the activity of caspase-8 linked to the death receptors fails to be increased in CFPAC-1 and BxPC-3 cells." (PMID 22745658, 2012). "We assessed published studies of the association between caspase 9 polymorphisms and cancer risk from nine studies with 5,528 subjects for rs4645978, six studies with 2,403 subjects for rs105276 and two studies for rs4645981." (PMID 22616010, 2012). "In current study, we first summarized the data about the association of intrinsic initiator CASP9 functional polymorphisms and cancer risks." (PMID 22616010, 2012). "Suppression of Akt in cancer cells is associated with activation of the mitochondrial apoptotic pathway involving the caspase-9-dependent caspase cascade." (PMID 22607709, 2012). "Main results of pooled ORs and stratification analysis of the rs4645978, rs1052576 and rs4645981 in caspase 9 on cancer risk." (PMID 22616010, 2012). "Caspase-9 and 3 were then activated, which cause apoptosis to cancer cells." (PMID 38827790, 2024). "Additionally, 17-AAG induces apoptosis by promoting the mitochondrial release of cytochrome C and Smac/DIABLO, activating caspase-9 and caspase-3, and causing a conformational change in Bax, underscoring its potential therapeutic uses in cancer treatment." (PMID 39204231, 2024). "Earlier and recent studies have showed that a high ratio of Bax to Bcl-2, activation of caspase family, including caspase-3, caspase-8 and caspase-9, as well as the loss of mitochondrial transmenbrane potiential are observed in monensin-induced apoptosis of several human cancer cell lines." (PMID 36896461, 2023). "However, other CASP9 polymorphisms (rs4645981 and rs1052571) have been associated with the risk of developing cancer." (PMID 37886944, 2023).
cancer (continued). "Fe3O4 nanoparticles induce apoptosis in cancer cells by raising the quantity of reactive oxygen species (ROS) and intracellular calcium, as well as boosting the expression of caspase-3 and caspase-9 and decreasing the expression of Bcl-2, as well as causing direct DNA damage." (PMID 35867269, 2023). "Furthermore, mechanism fraction 21 inhibited [A549] cancer cell proliferation by activating caspases, and the increased activity of caspase-3 and caspase-9 suggested that this fraction causes cytotoxicity in cancer cells via the apoptotic intrinsic pathway." (PMID 34834153, 2021). "Consequently, while multiple polymorphisms near the CASP9 locus associate with differential cancer risk, further study will need to clarify which, if any, of these variants cause pathogenic alterations in caspase-9 activity or expression." (PMID 34305609, 2021). "Mutation or loss of CASP9 heterozygosity is rarely observed in human cancers." (PMID 34305609, 2021). "The T allele at the CASP9 promoter SNP rs4645978 has been associated with increased risks of colorectal and gastric cancers, but decreased risks of breast cancer, acute myeloid leukemia, and pancreatic cancer." (PMID 34305609, 2021). "From the fluorescence images and quantitation of Fenton positive cells after 24 h, we can see regardless of SPION charge, all groups including Ferumoxytol induced significant Fenton reactions in the cancer cells, and caused high expression of caspase 9 (P < 0.005)." (PMID 32548111, 2020). "Therefore, the TNFα-induced upregulation of CASP9 via NF-κB-mediated FFL should be a molecular mechanism underlying the TNFα-promoted apoptosis of cancer cells induced by DOX." (PMID 32225068, 2020). "Taken into account that defect in apoptosis could cause cancer, the caspase family is essential to the process of apoptosis, we detected the activities of the initiator caspase-9 and the effector caspase-3 by Western blot." (PMID 30042171, 2018). "Besides the function it plays to decide cell survival during development and cell resistance to UV and γ-irradiation, there is also evidence that caspase-9 initiated apoptosis is believed to reflect the susceptibility of cancer cells to chemotherapy drugs." (PMID 28177918, 2017). "Moreover, previous studies demonstrated that CASP9 polymorphisms and expression were associated with prognosis of cancers." (PMID 28453560, 2017). "The up-regulated TNF-β, TNFRSFs (tumor necrosis factor receptor superfamily members) and Cytochrom C (Cyto C) in apoptosis antibody array implied that the cancer cell apoptosis was triggered by death receptors and transduced from a Cyto C/Apaf-1/Caspase-9 to Caspase-3 pathway linked to mitochondria." (PMID 27464624, 2016). "To examine whether the Ex5+32 G>A (rs1052576) polymorphism in the CASP-9 gene alters cancer risk, we conducted a comprehensive meta-analysis of 7 case-control studies consisting of a total of 1668 cancer cases and 2294 healthy controls." (PMID 23251262, 2013). "In the subgroup analysis by ethnicity, we found that the A allele and A allele carrier of Ex5+32 G>A in CASP-9 might decrease the risk of cancer in the Asian population (OR=0.60, 95% CI, 0.44–0.81, P<0.001; OR= 0.63, 95% CI, 0.44–0.90, P= 0.01; respectively)." (PMID 23251262, 2013). "In conclusion, this meta-analysis demonstrated that A allele and A allele carriers of the Ex5+32 G>A polymorphism in the CASP-9 gene may be protective factors for cancer risk." (PMID 23251262, 2013).
cancer (continued). "Hence, we performed a meta-analysis of all eligible studies to derive more precise estimation of the association of CASP9 SNPs with cancer risks." (PMID 22616010, 2012). "The fact that TRAIL regulation, if at all, was weak, whereas RIP up-regulation was relatively late occurring, suggests that especially the intrinsic pathways associated with caspase-9 and apoptosome activation may play an essential role in cancer cell death induction." (PMID 29876013, 2018). "However, we are still may unable to reach a consistent conclusion concerning the association between the CASP-9 Ex5+32 G>A (rs1052576) polymorphism and cancer risk according to previous studies." (PMID 23251262, 2013). "Stratified analyses revealed that the NKX3‐1 rs2228013, CASP9 rs1052571, CASP9 rs4645982, and CASP3 rs4647603 SNPs were all closely tied to the risk of this cancer type." (PMID 40344485, 2025). "It has been reported that sIL-24 induces apoptosis in the mitochondrial pathway by increasing the protein ratio of Bax/Bcl-2, increasing cytochrome C release, and up-regulating the expression of Caspase-9 and Caspase-3 in cancer cells." (PMID 40243937, 2025). "Targeting the BIR2 and BIR3 domains of XIAP and other IAPs, there are several SMAC mimetics in clinical trials, including AT406, TL32711 (birinapant), LCL161, AEG40826, CUDC427, and others to release active CASP3 and CASP9 to kill cancers." (PMID 40533441, 2025). "Gene expression analysis revealed upregulation of pro-apoptotic genes (BAX, Caspase 3, and Caspase 9) in cancer cells, alongside a decrease in anti-apoptotic BCL-2 expression." (PMID 39805861, 2025). "Ligand–receptor modeling revealed directional signaling via the SPP1–CD44 axis between CASP9-high cancer cells and macrophages." (PMID 41201629, 2025). "CK inhibits AKT1 activity, activates the expression of apoptotic proteases Caspase-3, Caspase-8, and Caspase-9, induces cancer cell apoptosis, and also inhibits cancer cell migration and invasion." (PMID 40422575, 2025). "These extracts promote apoptosis in cancer cells by enhancing the activity of caspase-3, caspase-7, caspase-8, and caspase-9." (PMID 40728967, 2025). "Both compounds are known to disrupt the mitochondrial membrane potential (MMP), promoting cytochrome c release and activation of the caspase cascade (caspase-9 → caspase-3) in cancer cells." (PMID 41226279, 2025). "CASP3 and CASP9, which are cysteine proteases, play a key role in apoptosis induction in various cancers." (PMID 40804316, 2025). "ST1326 sensitizes cancer cells to Bcl-2 inhibition, upregulates caspase-9, −8, and −3 mRNA and protein levels, and induces apoptosis; these effects have also been confirmed in canine cancer cell models." (PMID 41219902, 2025). "Disruption of ICAM-1–FGG interaction suppresses anti-apoptotic signaling and consequently activates caspase-9/3 pathway, leading to cancer cell death." (PMID 39168965, 2024). "D-Limonene and α-Pinene can activate the expression of Caspase-9 and Caspase-3, stimulating apoptosis in cancer cells." (PMID 39857347, 2024). "As a result, increased activation of caspase-9 and caspase-8 was recorded, together with stimulation of cancer cell apoptosis." (PMID 38339275, 2024). "Glabridin promotes tumor cell apoptosis by upregulating BAX, Caspase-3, Caspase-8, and Caspase-9 and downregulating Bcl-2, and inhibits cancer cell invasion and metastasis by downregulating N-Cadherin and upregulating E-Cadherin to reduce cell adhesion." (PMID 39723390, 2024).